PRSS50 (serine protease 50)
Description:
May be involved in proteolysis through its threonine endopeptidase activity.
Synonyms: CT20; TSP50
Tractability: Antibody: UniProt predicts a signal peptide or a membrane-spanning region.
Gene: Protein-coding gene on chromosome 3 (46,712,117 to 46,717,869, reverse strand). Ensembl gene ENSG00000283706.
Subcellular location: Endoplasmic reticulum
Gene Ontology:
Molecular function: threonine-type endopeptidase activity; serine-type peptidase activity; serine-type endopeptidase activity
Biological process: proteolysis; protein processing
Cellular component: cytoplasm; endoplasmic reticulum
Genetic constraint (gnomAD): Loss-of-function variants: 23 observed, 32.35 expected, observed/expected ratio (o/e) 0.71, 90% interval 0.51 to 1.01. The upper end of that interval is the gene's LOEUF score, 1.01, which puts it in group 4 of 6, group 1 being the genes least tolerant of losing a copy. Missense variants: 484 observed, 515.1 expected, observed/expected ratio (o/e) 0.94, 90% interval 0.87 to 1.01. Synonymous variants: 224 observed, 215.91 expected, observed/expected ratio (o/e) 1.04, 90% interval 0.93 to 1.16.
Homologues: Orthologues: chimpanzee PRSS50 (99% identical), macaque PRSS50 (82% identical), mouse Prss50 (62% identical), pig PRSS50 (62% identical), dog PRSS50 (61% identical), rat Prss50 (61% identical), guinea pig PRSS50 (58% identical). Paralogues in human: PRSS33 (23% identical), OVCH1 (23% identical), PRSS48 (22% identical), PLG (22% identical), PRSS27 (21% identical), TMPRSS12 (21% identical), PLAT (21% identical), PRSS57 (20% identical), KLK15 (19% identical), GZMM (19% identical), KLK9 (18% identical), PRSS37 (13% identical), and 2 more.
Diseases named in the same sentence as PRSS50 in open-access papers:
PRSS50 is named in the same sentence as 34 diseases in open-access papers, as found by Europe PMC text mining. Sharing a sentence is not in itself a finding about the gene and the disease. The quoted sentences say what the papers report.
breast cancer (14 papers, 2011 to 2025). A primary or metastatic malignant neoplasm involving the breast. "Overexpression of PRSS50 is associated with breast cancer invasion and malignancy, but it is not a top candidate for accessory breast aetiology." (PMID 41296379, 2025). "However, variants in two candidate genes, PRSS50 and FANCC, were prioritised as top candidates for the accessory breast phenotype in the family because these two genes have previously been implicated in breast diseases such as breast cancer." (PMID 41296379, 2025).
breast diseases (1 paper, 2025). "Among these, PRSS50 and FANCC emerged as top candidates, being implicated in breast diseases." (PMID 41296379, 2025). "Aside from PRSS50 and FANCC, numerous other aetiologic variants in 10 genes were found to segregate with the accessory breast phenotype in the family, even though these genes have not been previously linked to breast diseases." (PMID 41296379, 2025).
cancer (12 papers, 2015 to 2026). A tumor composed of atypical neoplastic, often pleomorphic cells that invade other tissues. "Despite its potential importance, PRSS50 remains underexplored in cancer research." (PMID 39136024, 2024). "However, in cancer cells, knockdown of PRSS50 resulted in impaired cell proliferation and increased levels of apoptosis." (PMID 35455681, 2022).
PRSS50 also shares sentences with these, for which no sentence is quoted: tumor (18 papers); colorectal cancer (6); gastric cancer (6); lymph node metastases (4); adenoma (3); cervical cancer (3); hepatocellular carcinoma (3); breast tumor (2); colorectal adenoma (2); lentivirus infection (2); liver cancer (2); cognitive decline (1); Cognitive impairment (1); colitis (1); colon cancers (1); inflammatory bowel disease (1); Insulin resistance (1); intestinal diseases (1); laryngeal carcinoma (1); liver disease (1); lung carcinoma (1); metastasis (1); metastatic cancer (1); metastatic tumor (1); neuroblastoma (1); neurodegenerative disease (1); non-small cell lung carcinoma (1); steatosis (1); testicular cancer (1); tubular adenoma (1).
A further 1 disease shares a sentence with PRSS50 in 1 paper.